CBX7 (chromobox 7)
Diseases named in the same sentence as CBX7 in open-access papers (continued):
Sharing a sentence is not in itself a finding about the gene and the disease.
tumor (continued). "Specifically, the median expression of CBX2 showed an evident increase with more advanced tumor stages in pRCC, while the median expression of CBX7 showed decreasing trends in both RCC subtypes." (PMID 36292141, 2022). "Our findings supported a different potential involvement of CBX6 in ccRCC and pRCC, and a similar tumor suppressive role for CBX7 in both assessed RCC subtypes." (PMID 36292141, 2022). "Our findings indicated that CBX1/3/8 are tumor promoters, while CBX7 serves as a tumor suppressor in ESCA." (PMID 35464847, 2022). "We found that 3.8% of top down-regulated DEGs in GKO tumours were CBX7 targets, including Wnt10a, CCNE1, FGFR2, and DUSP4." (PMID 35867177, 2022). "This strongly support our first observation of CBX3 being positively and CBX7 being negatively correlated with tumor stemness." (PMID 36361869, 2022). "Consistent with the in vitro study, the overexpression of CBX7 suppressed the tumor growth in mice compared with the lenti-NC." (PMID 35646140, 2022). "Except for CBX7, the mRNA levels of CBX1/2/3/4/5/6//8 was all significantly associated with tumor recurrence status." (PMID 35210369, 2022). "In combination with other studies, the current study demonstrated that CBX7 as a conserved tumour suppressor mediated the effects of miR-181 on liver tumour progression." (PMID 35867177, 2022). "Specifically, we observed significant upregulation of CBX1, CBX3, and CBX5 members, followed by robust downregulation of CBX7 in tumor tissues." (PMID 36361869, 2022). "For example, CBX2 and CBX7 have been shown to have contrasting roles in BCa metabolism and cell growth, with CBX2 being associated with aggressive tumour subtypes and poorer patient outcomes." (PMID 35884550, 2022). "Then, we showed that CBX7 inactivated the TNF signaling pathway to inhibit tumor proliferation and enhanced the sensitivity of ccRCC cells to TKIs." (PMID 35342353, 2022). "Further studies showed that CBX7 was negatively correlated with tumor stage, tumor grade, and tumor nodal metastasis status." (PMID 35464847, 2022). "The higher CBX7 expression group presented higher infiltration of immune which can kill tumor cells, including T cells, B cells, Cytotoxic cells, CD8 T cells, NK cells, iDC cells, Treg cells, and Th17 cells." (PMID 35464847, 2022). "We showed that levels of CBX7 protein were significantly increased in GKO tumours compared to WT tumours." (PMID 35867177, 2022). "We presumed that CBX7 target genes, at least some CBX7 target genes, would be down-regulated in miR-181 KO tumours compared to WT tumours if CBX7 was functional." (PMID 35867177, 2022). "For example, Hurtle adenoma is a rare differentiated thyroid tumor with the highest incidence of metastasis, and as the tumor worsens, CBX7 gradually decreases at the transcriptional level and the tumor develops into Hurtle carcinoma." (PMID 34659360, 2021). "Glycolytic metabolites, including glucose-6-phosphate, 3-phosphoglycerate, and fructose-6-phosphate, exhibited upregulated expression in high CBX2 and low CBX7 tumor samples." (PMID 34572770, 2021). "Taken together, our results indicate that CBX7 functions as a tumor suppressor to downregulate AKR1B10 and further inactivates ERK signaling." (PMID 34035231, 2021). "Floriana Forzati and colleagues reported that CBX7 is a tumor suppressor, and its inactivation promotes LUAD progression." (PMID 33686019, 2021). "In tumor immune microenvironments with high expression of CBX7, the infiltration of immune cells able to kill tumor cells increased, including B cells, cytotoxic cells, CD8+ T cells, NK cells, and macrophages." (PMID 34966411, 2021). "The results showed there was a trend for higher expression of CBX3 and CBX5 with the progression of LUAD, in terms of worse tumor grade, while the expression of CBX7 showed a decreasing trend." (PMID 34966411, 2021).
tumor (continued). "Our results showed that the expression levels of CBX7 and E-cad in the CC tissues were lower than those in the adjacent non-tumorous tissues, whereas the expression level of VIM was higher." (PMID 33748425, 2021). "Reduced CBX7 expression was shown to correlate with a high tumor grade in thyroid, pancreatic, breast, colon, and lung carcinomas." (PMID 34117289, 2021). "We also demonstrated for the first time that CBX7 acted as a tumor suppressor in UBC through the inhibition of cell proliferation, invasion, and stemness, via transcriptionally suppressing the expression of AKR1B10–ERK signaling." (PMID 34035231, 2021). "The results showed that when compared with normal tissues, the mRNA expression level of CBX7 was downregulated in tumor tissues with different stage, whereas CBX2/3/4/8 was upregulated." (PMID 34117289, 2021). "The high expression of CBX7 and the low and high expression levels of E-cad were higher in the adjacent non-tumor tissues, whereas the low and high expression levels of VIM were lower (P < 0.05)." (PMID 33748425, 2021). "While in tumor tissues, the higher grade of tumor is, the lower expression level of CBX7, but the higher expression level of AKR1B10 were detected." (PMID 34035231, 2021). "Taken together, these results strongly indicated that CBX7 functioned as a novel tumor suppressor in UBC." (PMID 34035231, 2021). "As a result, the tumor volumes and sizes were dramatically smaller in the CBX7-overexpressed T24 and UMUC-3 cells (p < 0.05)." (PMID 34035231, 2021). "An example is that a polycomb group protein CBX7 is oncogenic in hematological malignancies but plays tumor‐suppressive roles in certain epithelial‐based tumor contexts." (PMID 34938963, 2021). "With regard to regulation of gene expression, DNA methylation of levels CBX2/7 gene inversely and significantly correlated with CBX2 and CBX7 mRNA in tumor samples, suggesting the role of CpG methylation in regulation of their gene expression." (PMID 33400401, 2021). "By contrast, increased CBX2 and decreased CBX7 in tumor cells result in augmented glycolysis, which in turn supports tumor cell proliferation." (PMID 33400401, 2021). "Copy number analysis showed higher amplification frequency of CBX2 gene and almost negligible amplification of CBX7, suggesting oncogenic and tumor‐suppressive roles, respectively." (PMID 33400401, 2021). "In THCA, the loss of CBX7 expression was correlated with larger tumor size in THCA patients while CBX7 expression progressively decreased with malignancy grade and neoplasia stage." (PMID 33344640, 2020). "On one hand, higher mRNA and protein expressions of CBX7 were found in HCC tissues, and mRNA expression of CBX7 was significantly related with patients’ individual cancer stages and tumor grades." (PMID 30481161, 2018). "After 15 days, xenografted tumors were visible, and tumor size was counted and smaller size in CBX7 overexpressing groups." (PMID 28388562, 2017). "Specially, it has been reported that CBX7 inhibited breast tumorigenicity through DKK-1-mediated suppression of the Wnt signaling pathway, suggesting that CBX7 was a critical tumor suppressor in human BC." (PMID 29190923, 2017). "We found that CBX7 was abundantly expressed in most of the examined non-tumorous pancreatic tissues, while a small proportion of non-tumor tissues exhibited both cytoplasmic and nuclear expression of CBX7." (PMID 28030829, 2017). "In this study, we tested the relationship among CBX7 mRNA level, tumor grade and poor prognosis in CGGA, TCGA, REMBRANDT and GSE16011 datasets." (PMID 28460453, 2017). "In the present study, we found that the GpC protein CBX7 was a tumor suppressor during pancreatic tumorigenesis." (PMID 28030829, 2017). "It has been proven that CBX7 controls the growth and self-renewal of normal and tumor-derived prostate cells." (PMID 28388562, 2017). "Previous studies have demonstrated that CBX7 is involved in multiple cancer types as a tumor suppressor." (PMID 28388562, 2017).
tumor (continued). "Here, we present data that suggests CBX7 is an important inhibitor of β-catenin activation that blocks tumor cell migration and invasion by blocking EMT." (PMID 28388562, 2017). "We found that si-CBX7 treatment potentiated tumor aggressiveness in U251 cells compared with si-ctrl treatment." (PMID 28460453, 2017). "In cancer cells, cyclin E1 levels are up-regulated and, conversely, p16 levels was limited via various ways so that CBX7 acts as a tumor repressor in part of GBM cells." (PMID 28460453, 2017). "CBX7 promotes the proliferation of normal and tumor-derived prostate cells by repressing the transcription of the tumor suppressors p16Ink4a and p14ARF." (PMID 28030829, 2017). "CBX7 expression was significantly lower in advanced tumor stages (pT3 vs. pT2, p = 0.0013) and in tumors with high (> 7) compared to low (< 7) Gleason Scores (p = 0.0167)." (PMID 27449098, 2016). "Aberrant expression of miR-9 contributes to tumor cell invasion, partly through directly down-regulating CBX7 protein expression." (PMID 26870998, 2016). "Taken together, these data suggest that miR-375 leads to the activation of oncogenic signatures and tumor progression by targeting CBX7." (PMID 27449098, 2016). "CBX7 repression induced malignant progression and provides a rationale for the tumor promoting role of miR-375 in vitro and in vivo." (PMID 27449098, 2016). "Cbx7, yet another Chromobox protein, behaves rather ambiguously in different human malignancies owing to its dual role, both as an oncogene as well as a tumour suppressor." (PMID 27291091, 2016). "More studies are necessary to further elucidate the role of Cbx7 in tumor development and modulation." (PMID 25881303, 2015). "Several recent studies have reported the Polycomb Repressive Complex 1 member CBX7 as a tumor-suppressor gene whose expression progressively decreases in different human carcinomas in relation with tumor grade, malignant stage and poor prognosis." (PMID 25595895, 2015). "A causal network modeling meta-analysis further filtered this list down to only three genes, predicting UHRF1 and WHSC1 to be oncogenic master regulators of the cancer DNA methylome, and CBX7 to be a key tumor suppressor." (PMID 26169266, 2015). "The universal tumor suppressor role of the chromobox protein CBX7 is well supported by extensive literature in many different cancer types." (PMID 26169266, 2015). "In fact, it has been demonstrated that CBX7 acts both as an oncogene and a tumor suppressor gene depending on the cellular system in which it is expressed and on the different proteins interacting with it in the several tissues." (PMID 25595895, 2015). "Recent studies have utilized cbx7-knockout mice to validate the tumor suppressor role of cbx7 in liver and lung carcinogenesis." (PMID 25881303, 2015). "The tumor suppressor role of CBX7 has been very recently confirmed by the phenotype of Cbx7-null mice." (PMID 25190058, 2014). "CBX7 is an essential component of the polycomb repressive complex 1 (PRC1) involved in the control of histone methylation at tumour suppressor loci such as p16." (PMID 24875049, 2014). "Therefore, the loss of CBX7 expression could deregulate the composition of the AP-1 complex, which, in turn, could trigger a program of transcriptional alteration that culminate in the appearance of tumours." (PMID 24865347, 2014). "The tumour suppressor role of CBX7 has been very recently confirmed by the phenotype of cbx7 knockout mice." (PMID 24865347, 2014). "Unexpectedly, 9 genes showed the inverse association, including the tumor suppressor genes: RUNX1, CBX7, PRDX2 and PRDX3." (PMID 23077491, 2012). "CBX7 is a known tumor suppressor in both mice and humans and several PRDXs have been shown to have tumor preventive functions." (PMID 23077491, 2012). "In vivo experiments confirmed that CBX7 suppresses tumor formation." (PMID 39988672, 2025). "In summary, these data support the tumor-suppressive function of CBX7 in vivo." (PMID 39988672, 2025).
tumor (continued). "We found that CBX7 mRNA expression levels in these cells somewhat were inversely correlated with tumor volume; xenografts with higher CBX7 expression grew more slowly than those with lower CBX7 expression (except for G6), indicating that higher CBX7 levels are associated with reduced tumorigenicity." (PMID 39988672, 2025). "The silencing of CBX7 in PDAC suggests that CBX7 could function as a tumor suppressor, and its reduced expression likely aids in the development and progression of PDAC." (PMID 40387566, 2025). "Among them, CBX7 was the most significantly downregulated gene in tumor-propagating cells (TPC)." (PMID 39988672, 2025). "Notably, we demonstrate for the first time that CBX7 exerts its tumor‐suppressive function in PDAC by inhibiting ERK phosphorylation, thereby suppressing cell proliferation, migration, and invasion." (PMID 40387566, 2025). "In pancreatic ductal adenocarcinoma (PDAC), CBX7 inhibits tumor progression by upregulating PTEN (Phosphatase and Tensin Homolog) expression, thereby negatively regulating the PI3K/AKT signaling pathway in Panc-1 and MIA PaCa-2 cell lines, as well as in nude mice." (PMID 40175347, 2025). "Overexpression of CBX7 inhibits tumorigenicity, while its depletion promotes tumor growth." (PMID 41153362, 2025). "In general, CBX1/2/3/4/5/6/8 are tumor promoting factors in most cancers, and CBX7 is tumor-suppressing factor in almost all cancers, thus CBXs could serve as diagnostic and prognostic biomarkers." (PMID 40302984, 2025). "Based on the sequencing results and the fact that CBX7 regulates stem cell differentiation and renewal, we hypothesized that CBX7 promotes tumor development and drug resistance by impacting ESCC stemness." (PMID 38413558, 2024). "We identified CBX7, a known target of miR-181a/b1, as upregulated in miR-181a/b1 KO tumours." (PMID 39120319, 2024). "Previously, we reported that CBX7 has tumor suppressor functions." (PMID 38037081, 2023). "Other DNMT inhibitors that have not yet progressed to clinical trials include chromobox 7 (CBX7), which has been shown to cause tumour suppression in vitro, and CM-272, which can cause tumour and metastasis regression in in vivo transgenic mouse models." (PMID 36980741, 2023). "In conclusion, in this study we demonstrate that adipose-derived exosomal miR-421 within the tumor microenvironment downregulates CBX7 and consequently may enhance OC metastatic potential." (PMID 38037081, 2023). "The expression of CBX7 and Ki-67 in tumor tissues was detected by immunohistochemistry." (PMID 35646140, 2022). "On the other hand, we observed significant negative association between a high CBX7 expression and higher tumor grade in LIHC and PAAD tumors." (PMID 36361869, 2022). "Interestingly, it was subsequently shown that the expression of this miRNA enhances the proliferation of tumor cells through the repression of the CBX7 protein, which acts as a tumor suppressor." (PMID 35804851, 2022). "However, normal tissues had the highest mRNA expression of CBX7, and the mRNA expression of CBX7 tended to be lower as tumor nodal metastasis status increased." (PMID 35464847, 2022). "RNF26 promoted the degradation of CBX7 and enhanced ccRCC tumor growth." (PMID 35342353, 2022). "Expression levels of seven CBX7 targets, namely Wnt10a, Ccne1, Fgfr2, Bhlhe22, Klhdc8a, Pde10a, and Dusp4, which had been significantly inhibited in miR-181ab1 KO compared to WT tumours in mice, were also significantly lower in either iClust2 or iClust3 than iClust1 HCCs." (PMID 35867177, 2022). "While, the TNFα/NF-kappa B signaling was not the only pathway for CBX7 to inhibit the tumor growth in ccRCC, the underlying mechanism by which CBX7 modulates the cancer progression needs to be performed in the furture." (PMID 35342353, 2022). "Stable expression of CBX7 was evidenced in the majority of tumour cells at the end of experiments." (PMID 35867177, 2022).
tumor (continued). "Prior studies have demonstrated that CBX7 exerts tumor-suppressing properties in most malignancies." (PMID 36140750, 2022). "Mechanically, CBX7 may exert its tumor suppressor role by inhibiting the Wnt pathway and subsequently restrain the malignant character in LUAD." (PMID 36324565, 2022). "CBX7-mediated tumour suppression is in part through inhibition of of cyclin E1." (PMID 35867177, 2022). "Hypermethylated promoter regions in ALK tumor cells showed strong enrichment of binding sites for proteins associated with chromatin remodeling in ESC, in particular PRC associated proteins including CBX7, EZH2, MTF2, PHF19, RING1B, RNF2, and SUZ12." (PMID 33310759, 2021). "In summary, these data supported the tumor-suppressive function of CBX7." (PMID 34035231, 2021). "The present study suggested that CBX6 and CBX7 could function as both oncogenes and tumor suppressors, depending on the tumor type and cellular context." (PMID 34395271, 2021). "The frequent downregulation of CBX7 in UBC tissues suggested that CBX7 may function as a tumor suppressor." (PMID 34035231, 2021). "CBX7 silencing in UBCs suggested that CBX7 might act as a tumor suppressor, and its downregulation probably contributes to the development and progression of UBC." (PMID 34035231, 2021). "Then, we demonstrated that suppression of AKR1B10 by siRNA could reverse the tumor promoting effect induced by CBX7 knockdown on cell proliferation, invasion, and stemness." (PMID 34035231, 2021). "For instance, in many cancers CBX2/CBX8 are oncogenic while CBX6/CBX7 are tumor suppressive." (PMID 34617019, 2021). "With the increase of tumor grade, the expression of CBX7 mRNA shows a downward trend." (PMID 34659360, 2021). "The expression of CBX7 may serve as a valuable tool in the clinical assessment of tumor biological behavior and disease prognosis in patients with CC." (PMID 33748425, 2021). "CBX7 was downregulated in tumor samples compared with the normal counterpart (P < 0.05)." (PMID 33082469, 2020). "However, the highest mRNA expression of CBX7 was found in grade 1, and as tumor grade increased, the mRAN expression of CBX7 tended to be lower." (PMID 30481161, 2018). "CBX7 may act as an oncogene or a tumor suppressor, depending on the cellular context and cancer types." (PMID 29422082, 2018). "Furthermore, as a tumor suppressor, CBX7 expression is pivotal to reduce tumor invasion and evaluate prognosis." (PMID 28388562, 2017). "Here, we found that CBX7 is a critical tumor suppressor that silences Wnt/β-catenin signaling; CBX7 overexpression decreases nuclear β-catenin levels and deblocks translocation from the nucleus to the cytoplasm, while minimally affecting total β-catenin levels." (PMID 28388562, 2017). "In this study, we have envisaged the hypothesis that CBX7 tumor suppressor or oncogenic role may be also mediated by the regulation of miRNA expression since the role of miRNAs in cancer development and progression has been frequently reported." (PMID 28259135, 2017). "This role is supported from the development of benign and malignant neoplasias in Cbx7 null mice." (PMID 28259135, 2017). "However, other studies have shown that CBX7 expression is inversely correlated with malignancy grade and neoplasia stage in thyroid neoplasia." (PMID 28030829, 2017). "A crucial activity of CBX7 in tumor progression is supported by several studies." (PMID 28259135, 2017). "Taken together, these data suggest that the oncogenic properties of miR-375 might be explained by its targeting of CBX7, as CBX7 expression was significantly decreased in primary tissues with high Gleason Scores and in those with advanced tumor stages." (PMID 27449098, 2016).